MPO (myeloperoxidase)
Diseases named in the same sentence as MPO in open-access papers (continued):
Sharing a sentence is not in itself a finding about the gene and the disease.
ANCA-associated vasculitis (continued). "These days, data from MAINRITSAN3 point in the direction of treatment for a total 4 years for PR3-ANCA-associated vasculitis and initially severe and relapsing MPO-ANCA-associated vasculitis, and 2 years for newly diagnosed severe MPO-ANCA-associated vasculitis." (PMID 33372616, 2020). "MPO-ANCA is the major pathogenic autoantibody in ANCA-associated vasculitis (AAV)." (PMID 29929470, 2018). "In the present study, we investigated the expression of claudin-1 and its colocalization with ZO-1 in various human glomerular diseases including IgA nephropathy, purpura nephritis, ANCA associated vasculitis (MPO-ANCA and PR-3 ANCA), anti-GBM-RPGN, and lupus nephritis." (PMID 24868462, 2014). "Increasing evidence has suggested that linear epitopes of antineutrophil cytoplasmic antibody (ANCA) directed to myeloperoxidase (MPO) might provide clues to the pathogenesis of propylthiouracil (PTU)-induced ANCA-associated vasculitis (AAV)." (PMID 24252385, 2013). "A previous nationwide survey of the Japanese population showed that CY was used by 62.3 % of MPA and 96.3 % of GPA patients, and a recent study of Japanese patients with MPO-ANCA-associated vasculitis (JMAAV) also reported that 58.3 % of the patients were treated with CY." (PMID 22760432, 2013). "Furthermore, in an animal model of MPO-ANCA associated vasculitis, it was demonstrated that T cells play a pivotal role in the pathophysiology of the disease." (PMID 19381293, 2009). "Furthermore, given the shared genetic basis of MPO-ANCA-associated vasculitis (AAV) and MPO-positive EGPA, neutrophilic vasculitis may also arise as a primary phenomenon." (PMID 40632386, 2025). "Increasing evidences have suggested the pathogenic role of anti-neutrophil cytoplasmic antibodies (ANCA) directing myeloperoxidase (MPO) in ANCA-associated vasculitis (AAV)." (PMID 23577119, 2013). "In addition, epitope mapping of MPO, especially linear epitopes, might also provide clues to the pathogenesis of MPO-ANCA-associated vasculitis." (PMID 23577119, 2013). "An induction regimen involving rituximab, a short course of low-dose oral cyclophosphamide, and a rapid prednisone taper was used in 129 patients with ANCA-associated vasculitis (AAV), 70% of whom had myeloperoxidase (MPO)-ANCA and 9% had relapsing disease." (PMID 40003652, 2025). "This study investigates the value of MPO-ANCA status at baseline and follow-up as a predictive marker for clinical relapse in ANCA-associated vasculitis." (PMID 40959075, 2025). "For instance, anti-neutrophil cytoplasmic antibodies specific for proteinase 3 (PR3-ANCA) and myeloperoxidase (MPO-ANCA) can induce neutrophil activation, leading to ANCA-associated vasculitis." (PMID 41425580, 2025). "Both proteinase 3-ANCA (PR3-ANCA) and myeloperoxidase-ANCA (MPO-ANCA) were within normal limits, ruling out ANCA-associated vasculitis." (PMID 40755567, 2025). "ANCA-associated vasculitis (AAV) is an AID characterized by serum-positive ANCA, better known as MPO- or PR3-AAV, and the rapidly progressive glomerulonephritis which shows pauci-immune complex deposition in pathogenic biopsy." (PMID 37603715, 2024). "HLA-DRB1*11 was reported to be a susceptible allele conferring the risk of myeloperoxidase (MPO) antineutrophil cytoplasmic antibody (ANCA)-associated vasculitis (AAV), i.e., MPO-AAV, in a Chinese population." (PMID 37686189, 2023). "Neutrophil cell death releases the key autoantigens in ANCA associated vasculitis (AAV); myeloperoxidase (MPO) and proteinase 3 (PR3)." (PMID 33790907, 2021). "In ANCA-associated vasculitis, IL-17A and IL-21 are influenced by Th17 effector T cells and increased in PR3-ANCA vasculitis and elevated IL-17A levels are found in MPO-ANCA vasculitis." (PMID 33023023, 2020). "Epigenetic factors including low DNA methylation in regulating MPO and PR3 transcription have also been found to be associated with ANCA-associated vasculitis." (PMID 33023023, 2020).
ANCA-associated vasculitis (continued). "Propylthiouracil (PTU) has been associated with drug-induced ANCA-associated vasculitis (AAV), with antibodies against myeloperoxidase (MPO) and proteinase 3 (PR3) present individually and together having been recognised." (PMID 32703233, 2020). "It was demonstrated that ANCA serotyping distinguishes distinct classes of ANCA disease: PR3-ANCA-associated vasculitis (PR3-AAV), MPO-ANCA-associated vasculitis (MPO-AAV), and ANCA-negative vasculitis." (PMID 31544837, 2019). "Anti-neutrophil cytoplasmic autoantibodies (ANCA) directed against myeloperoxidase (MPO) and proteinase 3 (PR3) are pathogenic in ANCA-associated vasculitis (AAV)." (PMID 30818380, 2019). "About 40% of EGPA patients have perinuclear ANCA antibodies against myeloperoxidase (MPO), resulting in the classification of EGPA as an ANCA-associated vasculitis." (PMID 28496445, 2017). "EGPA is categorized as an antineutrophil cytoplasmic antibody (ANCA)-associated vasculitis (AAV), but only 35–40 % of EGPA patients are reported to be ANCA positive, mostly are MPO-ANCA positive." (PMID 27461086, 2016). "The C- and P-ANCA in human patients with ANCA-associated vasculitis are mainly directed against proteinase 3 (PR3) and myeloperoxidase (MPO), respectively, and seem to be associated with disease activity." (PMID 25225805, 2014). "MPA is an ANCA-associated vasculitis (AAV), in which pauci-immune crescentic glomerulonephritis develops with generation of MPO-ANCA." (PMID 23162551, 2012). "The disease activity of both MPO-ANCA-associated vasculitis and RA was later controlled without prednisolone." (PMID 41939544, 2026). "An increased serum level of the MPO–DNA complex has also been found in other autoimmune diseases, such as rheumatoid arthritis, Behcet’s disease, and ANCA-associated vasculitis, but still without any dependence on skin condition." (PMID 39409000, 2024). "ANCA-associated vasculitis (AAV) is a systemic inflammatory disease of small- and medium-sized vessels, driven by autoantibodies targeting neutrophil proteins such as proteinase 3 (PR3) and myeloperoxidase (MPO)." (PMID 39857611, 2024). "These metabolic changes may underlie pathologic immune activation in ANCA associated vasculitis, as well as potentially contributing to the differing clinical phenotype between PR3- and MPO-ANCA positive patients." (PMID 33015103, 2020). "In this single centre retrospective study, we report the clinical outcomes in 8 patients with de novo or recurrent MPO-ANCA associated vasculitis and severe renal involvement treated with RTX with no CYC association." (PMID 31088509, 2019). "This is in line with our previous observation that, in a model of MPO-ANCA-associated vasculitis, repertaxin treated mice were not protected from hematuria, albuminuria or glomerular crescent formation." (PMID 22152684, 2011). "For instance, histone modifications at the MPO and PRTN3 gene loci may contribute to the pathogenesis of ANCA-associated vasculitis; DNA methylation levels at the PRTN3 promoter can also predict remission and recurrence in ANCA-associated vasculitis." (PMID 41425580, 2025). "ANCA-associated vasculitis (AAV) encompasses a group of multisystem autoimmune diseases characterised by necrotising small-vessel vasculitis and the presence of circulating autoantibodies (ANCAs) directed against the neutrophil cytoplasmic antigens proteinase 3 (PR3) and myeloperoxidase (MPO)." (PMID 36906660, 2023). "In addition, patients with ANCA-associated vasculitis, but not control subjects, had circulating MPO-DNA complexes." (PMID 24959541, 2013). "ANCA appears to be closely related to ANCA-associated vasculitis, but not all ANCA-associated vasculitis patients have ANCA, and the detection rate of ANCA has been lower than expected: MPO-ANCA in 30~80% of MPA patients and 0~10% of GPA patients." (PMID 32867138, 2020).
ANCA-associated vasculitis (continued). "Cases positive for ANCA may demonstrate myeloperoxidase antibody or proteinase-3 (PR3) antibody, both, or neither, and may be termed LAC-induced ANCA-associated vasculitis (AAV)." (PMID 37375793, 2023). "The first study found that both major histocompatibility-complex (MHC) and non-MHC are associated with ANCA-associated vasculitis and also that anti-PR-3 ANCA is associated with HLA-DP and the genes encoding α1 antitrypsin and PR-3, while anti-MPO ANCA is associated with HLA-DQ." (PMID 24959541, 2013).
myocardial infarction (107 papers, 2007 to 2025). Gross necrosis of the myocardium, as a result of interruption of the blood supply to the area, as in coronary thrombosis. "The loss of MPO in vivo, leads to reduced neovascularization after myocardial infarction, it partakes in mesenchymal activation of ECs in vivo, similar to TGFβ." (PMID 38322992, 2024). "The primary objective of this investigation was to delineate the therapeutic potential of BETNs for cognitive impairment associated with myocardial infarction (MI) by considering myeloperoxidase (MPO) a pivotal inflammatory biomarker." (PMID 39204198, 2024). "Evidence implicated NETs and NETs-related factors such as dsDNA, MPO/DNA complexes with myocardial infarction, and serious cardiac events." (PMID 37444400, 2023). "MPO, an enzyme released by activated neutrophils, has been linked to ventricular dysfunction and remodeling after myocardial infarction (MI), indicating its role as a marker of cardiac stress and remodeling." (PMID 38203681, 2023). "Mouse studies have previously shown that MPO can contribute to detrimental cardiac remodeling and fibrosis, and conversely that MPO deficiency can preserve cardiac function in myocardial infarction models." (PMID 38004170, 2023). "This stage is the promoter of foam cell formation in atherosclerosis, which makes MPO a marker of atheroma plaque instability correlated with the risk of developing myocardial infarction in the future." (PMID 33238444, 2020). "Recently, MPO has been found to be implicated in a multitude of diseases, including atherosclerosis, myocardial infarction, atrial fibrillation, multiple sclerosis, Alzheimer’s disease, lung cancer, and transplant rejection." (PMID 23861842, 2013). "By using mouse models of myocardial infarction, multiple sclerosis, and steatohepatitis (diseases in which MPO has been implicated in humans), we validated the high specificity and sensitivity of this assay." (PMID 23861842, 2013). "Therefore, both MPO and its reactive oxidants have been implicated in myocardial infarction, which contributes to matrix degradation and oxidative stress, and modulate macrophage activation toward a pro-inflammatory phenotype." (PMID 41226611, 2025). "In addition, plasma MPO levels are strongly associated with the prognosis and severity of myocardial infarction and are important biomarkers for identifying high‐risk patients." (PMID 39087342, 2024). "The diagnostic and prognostic impairment of myeloperoxidase serum level has also been documented.Therefore, it is of interest to document the correlation between myeloperoxidase and troponin T in young Indian patients with myocardial infarction." (PMID 35815198, 2022). "Elevated plasma MPO levels were associated with acute myocardial infarction." (PMID 31447863, 2019). "Since elevated levels of MPO predict the risk of myocardial infarction in patients with chest pain, increased endothelial exocytosis due to MPO catalyzed nitration of ApoA-I may provide a mechanistic link between MPO and acute coronary syndromes." (PMID 26680360, 2015). "The acute arterial occlusion that is an hallmark of myocardial infarction could contribute in these patients to protect neutrophils newly emerged from the bone marrow, preventing MPO release." (PMID 22761804, 2012). "NETs, composed of extracellular DNA decorated with histones and neutrophil-derived proteins such as MPO and elastase, are increasingly recognized as critical paracrine modulators of macrophage function after myocardial infarction." (PMID 41226611, 2025). "We examined the distribution of Il1r2 in sham-operated group and different stages of myocardial infarction, 1 day, 3 days, 14 days after MI, and found Il1r2 was co-expressed with MPO, as the fluorescent microscopy analysis displayed." (PMID 40231027, 2025).
myocardial infarction (continued). "Experimental studies with MPO knockout mice or oral MPO inhibitors showed reduced left ventricle dilation and improved left ventricular function in myocardial infarction models, indicating MPO's role in developing chronic heart failure." (PMID 40360833, 2025). "Neutrophil activation, degranulation, and release of MPO have been reported in arterial thrombosis, such as unstable angina and acute myocardial infarction, owing to their suspected proatherogenic nature." (PMID 39810847, 2024). "Recruitment of neutrophils leads to increased concentrations of MPO, and the oxidant produced by MPO can lead to impaired myocardial function and poor ventricular remodeling after myocardial infarction." (PMID 39050842, 2024). "Therapeutic inhibition of MPO has been shown to have a protective effect on cardiac function in mice with myocardial infarction by reducing neutrophil and monocyte infiltration." (PMID 39087342, 2024). "Both MPO-knockout models and MPO inhibitors lead to reduced neutrophils recruitment, and improved ventricular function and remodeling in myocardial infarction." (PMID 39050842, 2024). "MPO-knockout mice exhibit reduced number of ECs at scar sites following myocardial infarction, indicating reduced neovascularization." (PMID 38322992, 2024). "MPO inhibition showed protective effects on cardiac function after myocardial infarction and is currently subject to (pre)clinical studies." (PMID 38736886, 2024). "Neutrophil activation, degranulation, and markers of MPO release are now widely used as biomarkers for unstable angina and acute myocardial infarction, which are thought to be proatherogenic and play a role in destabilizing atherosclerotic plaques." (PMID 39810847, 2024). "For instance, Dan-Shen injection exerts anti-inflammatory effects by decreasing the expression of MMP2, MMP9, and myeloperoxidase (MPO) in a rat model of post-myocardial infarction." (PMID 38794213, 2024). "Currently, a specific MPO inhibitor is under clinical investigation, which emphasizes the need to advance anti‐inflammatory therapy after myocardial infarction." (PMID 39087342, 2024). "In this respect, previous studies found that MPO–DNA is a component of coronary thrombus in acute myocardial infarction and correlates with the presence of severe coronary atherosclerosis." (PMID 36979845, 2023). "We and others have shown that MPO mediates cardiac monocyte/macrophage recruitment and activation after myocardial infarction." (PMID 37656254, 2023). "Most importantly, MPO appears more and more as a reliable marker of myocardial infarction, and it is known to promote tissue injuries." (PMID 35186101, 2022). "Reduced levels of C-reactive protein (CRP) and myeloperoxidase (MPO) in the rats started from day 4 after the induction of myocardial infarction." (PMID 35684249, 2022). "It is of interest to document the correlation of myeloperoxidase (MPO) and Troponin T (TnT) in young Indian patients with myocardial infarction using epidemiological data." (PMID 35815198, 2022). "Correspondingly, the plasmatic levels of MPO were reported higher in various diseases such as cancer, or in patients after myocardial infarction." (PMID 35453861, 2022). "Myeloperoxidase (MPO) and trimethylamine N-oxide (TMAO) are novel biomarkers of different pathophysiological processes of acute myocardial infarction, and each of them predicts risk of adverse clinical outcomes." (PMID 34650427, 2021). "It was concluded that Annexin A1 upregulation inhibits neutrophil infiltration and MPO activity likely via the activation of STAT3 signaling pathway in the rat model of myocardial infarction." (PMID 34943928, 2021). "In myocardial infarction, the local presence of MPO as part of the early neutrophil infiltration into the infarction zone argues for a role of the enzyme in post-infarction remodeling." (PMID 33916434, 2021).